U6 (U6 spliceosomal RNA )
Gene: Small nuclear RNA gene on chromosome 4 (13,051,342 to 13,051,411, forward strand). Ensembl gene ENSG00000283271.
Homologues: Orthologues: chimpanzee U6 (100% identical), guinea pig U6 (73% identical), mouse Gm24382 (71% identical), mouse Gm54860 (67% identical). Paralogues in human: RNU6-536P (89% identical), RNU6-199P (87% identical), RNU6-1060P (86% identical), RNU6-1095P (86% identical), RNU6-1243P (86% identical), RNU6-140P (86% identical), RNU6-24P (86% identical), RNU6-270P (86% identical), RNU6-656P (86% identical), RNU6-686P (86% identical), RNU6-738P (86% identical), RNU6-748P (86% identical), and 1286 more.